LILRB1 (leukocyte immunoglobulin like receptor B1)
Description:
Receptor for class I MHC antigens. Recognizes a broad spectrum of HLA-A, HLA-B, HLA-C, HLA-G and HLA-F alleles. Receptor for H301/UL18, a human cytomegalovirus class I MHC homolog. Ligand binding results in inhibitory signals and down-regulation of the immune response. Engagement of LILRB1 present on natural killer cells or T-cells by class I MHC molecules protects the target cells from lysis. Interaction with HLA-B or HLA-E leads to inhibition of FCER1A signaling and serotonin release. Inhibits FCGR1A-mediated phosphorylation of cellular proteins and mobilization of intracellular calcium ions. Recognizes HLA-G in complex with B2M/beta-2 microglobulin and a nonamer self-peptide. Upon interaction with peptide-bound HLA-G-B2M complex, triggers secretion of growth-promoting factors by decidual NK cells. Reprograms B cells toward an immune suppressive phenotype.
Synonyms: LIR-1; ILT-2; MIR-7; CD85j; ILT2; LIR1; MIR7; CD85; PIRB; PIR-B
Gene: Protein-coding gene on chromosome 19 (54,616,309 to 54,638,022, forward strand). Ensembl gene ENSG00000104972.
Subcellular location: Cell membrane; Secreted (Isoform 5)
Pathways (Reactome):
Immune System: Immunoregulatory interactions between a Lymphoid and a non-Lymphoid cell
Genetic constraint (gnomAD): Loss-of-function variants: 60 observed, 69.04 expected, observed/expected ratio (o/e) 0.87, 90% interval 0.7 to 1.08. The upper end of that interval is the gene's LOEUF score, 1.08, which puts it in group 4 of 6, group 1 being the genes least tolerant of losing a copy. Missense variants: 803 observed, 771.55 expected, observed/expected ratio (o/e) 1.04, 90% interval 0.98 to 1.1. Synonymous variants: 328 observed, 300.27 expected, observed/expected ratio (o/e) 1.09, 90% interval 1 to 1.2.
Homologues: Orthologues: chimpanzee LILRB1 (90% identical), chimpanzee LILRA3 (54% identical), rat Pirb (47% identical), rat Lilrb3 (39% identical), mouse Pira12 (36% identical), mouse Pirb (36% identical), mouse Pira13 (35% identical), mouse Pira2 (35% identical), mouse Pira1 (35% identical), mouse Lilra6 (35% identical), rat LOC134485274 (34% identical), rat Lilrb2 (34% identical), and 3 more. Paralogues in human: LILRB2 (78% identical), LILRB3 (68% identical), LILRB5 (62% identical), LILRA1 (58% identical), LILRA2 (56% identical), LILRA6 (48% identical), LILRB4 (47% identical), LILRA4 (45% identical), KIR3DL1 (25% identical), KIR3DL2 (25% identical), KIR3DL3 (23% identical), LILRA5 (23% identical), and 13 more.
Diseases named in the same sentence as LILRB1 in open-access papers:
LILRB1 is named in the same sentence as 115 diseases in open-access papers, as found by Europe PMC text mining. Sharing a sentence is not in itself a finding about the gene and the disease. The quoted sentences say what the papers report.
HCMV infection (11 papers, 2012 to 2025). "In the same line, increased proportions of LILRB1+ (LIR-1+) NK cells were originally associated with HCMV infection in lung transplant recipients." (PMID 28261220, 2017). "Collectively, the inhibitory input triggered by UL-18 + LILRB1 interaction and the varying strength of inhibition governed by LILRB1 polymorphisms, promote successful evasion from NK cell killing to establish chronic HCMV infection." (PMID 31627371, 2019). "During persistent HCMV infections, LILRB1 expression is elevated on HCMV-specific CD8+ cytotoxic T cells (CTLs) with differentiated effector memory phenotype." (PMID 27584579, 2016).
malaria (10 papers, 2018 to 2025). Malaria is a serious and sometimes fatal disease caused by a parasite that commonly infects a certain type of mosquito which feeds on humans. "Elucidating the interactions between RIFINs and LILRB1/LILRB2 not only sheds light on the immune evasion strategies of P. falciparum but also provide novel insights for the development of malaria treatments and vaccines." (PMID 40860159, 2025). "In malaria-prone regions, antibodies containing LILRB1, similar to those with LAIR1, have been identified in patients." (PMID 38933531, 2024). "Antibodies containing LAIR1 and LILRB1 inserts represent a class of naturally occurring antibodies in humans, characterized by their broad-spectrum binding to the malignant malaria parasite’s RIFIN proteins." (PMID 38933531, 2024). "The presence of LAIR1/LILRB1 in public antibodies opens new perspectives on how the malignant malaria parasite manipulates host’s immune cell functions." (PMID 38933531, 2024). "A subset of adaptive NK cells characterized by the lack of CD56 (NCAM1) and higher expression of inhibitory receptors LAG3 (CD223) and LILRB1 (CD85j) correlated with reduced parasitemia and protection against malaria symptoms in the subsequent year." (PMID 37939134, 2023). "Receptor-containing antibodies with a portion of the LAIR1 and LILRB1 exons were produced in malaria patients in malaria-endemic areas." (PMID 35784341, 2022). "Binding extent of LILRB1 to host cell surface expressed RIFINs in malaria patients (small sample size) also shows direct correlation with disease severity." (PMID 29770278, 2018). "Moreover, people living in malaria-endemic areas across Africa have unique antibodies, containing exons of LILRB1 and LAIR1, which can bind multiple RIFINs4,6,7." (PMID 40500441, 2025). "It would be thus interesting to test whether inhibition of LILRB2 and maybe LILRB1 and Tim3 could help restore the phagocytosis capacity of monocytes during the first days of CM and limit malaria severity." (PMID 38835780, 2024). "Discoveries about interaction of RIFINs with LILRB1 and LAIR1 inhibitory receptors to promote parasite survival and suppress host immune effector molecules are likely to be important landmarks in completely unraveling malaria pathogenesis." (PMID 29770278, 2018). "Higher expression of LILRB1 and LILRB2 on intermediate and non-classical monocytes at 18 and 24 months during active malaria." (PMID 35911674, 2022). "The concomitant presence of IL-10 and a higher expression of LILRB1 and LILRB2 on non-classical monocytes suggests a down regulation of the cells involved in inflammatory mechanisms and therefore a potentially decreased ability to protect the infants from malaria." (PMID 35911674, 2022).
melanoma (10 papers, 2014 to 2025). A malignant, usually aggressive tumor composed of atypical, neoplastic melanocytes. "HLA-G expression in melanoma cells signaling through ILT2 (LILRB1) prevented NK cell cytolysis in vitro." (PMID 40849493, 2025). "Thus, increased expression of LILRB1 was reported in nearly half of malignant melanoma patients after treatment with the PD-1 directed antibody nivolumab." (PMID 37781391, 2023). "The anti-LILRB1 antibody GHI/75 has shown potential to enhance T cell cytotoxic activity mediated by an [anti-MART-1 × CD3] BiTE molecule by disrupting the interaction of LILRB1 with HLA-G expressed by malignant melanoma cells." (PMID 37781391, 2023).
gastric cancer (8 papers, 2015 to 2024). A primary or metastatic malignant neoplasm involving the stomach. "In gastric cancer for example, elevated LILRB1 expression was associated with advanced tumor stages, increased risk of recurrence and inferior survival." (PMID 37781391, 2023). "In conclusion, LILRB1+ M2 TAMs were associated with a pro-tumor immune contexture and determine poor prognosis in gastric cancer." (PMID 34485116, 2021). "Furthermore, high LILRB1 expression has been associated with both more advanced stages of gastric cancer and infiltration of M2 tumour-associated macrophages." (PMID 36900335, 2023). "The analysis of the tumor microenvironment in gastric cancer revealed that LILRB1-positive TAM had an M2-like phenotype." (PMID 37781391, 2023). "In gastric cancer, immunofluorescence analyses have shown that M2 TAMs are the primary immune cell expressing LILRB1." (PMID 36900335, 2023). "We analyzed the immunohistochemistry data of 166 gastric cancer patients to determine the clinicopathologic and survival significance of LILRB1." (PMID 34485116, 2021). "Expression of LILRB1 on gastric cancer cell lines induces resistance to NK cell cytotoxicity." (PMID 38022598, 2023). "Leukocyte immunoglobulin like receptor subfamily B1 (LILRB1) is considered to be an immunosuppressive molecule, which is an important receptor of human leukocyte antigen G. However, the clinical significance of LILRB1 expression in gastric cancer remains unexplored." (PMID 34485116, 2021). "LILRB1 and LILRB4 are also expressed on human primary gastric cancer specimens compared to healthy tissue, with high expression correlating with advanced disease." (PMID 38022598, 2023). "LILRB1 is found on a variety of cancers including breast and prostate cancers, hepatocellular carcinoma, B cell lymphoma, acute myeloid leukaemia (AML), acute lymphoblastic leukaemia (ALL) and gastric cancer cell lines." (PMID 38022598, 2023). "Thus, LILRB1 expression was reported in AML, certain T cell lymphomas, B-lineage lymphomas and leukemias, gastric cancer, ovarian cancer, and renal cell carcinoma." (PMID 37781391, 2023).
viral infections (8 papers, 2019 to 2024). "LILRB1 is similarly increased in viral infections, and has been associated with improved viral suppression in vitro." (PMID 35223535, 2022). "The lack of studies regarding LILRB2 but also LILRB1 polymorphisms in vertical transmission and viral infections makes it difficult to discuss the role of variants in this matter." (PMID 35877415, 2022).
endometriosis (7 papers, 2018 to 2023). The growth of functional endometrial tissue in anatomic sites outside the uterine body. "In endometriosis, genetic variants in HLA-G and LILRB1/2 are suggested to contribute to the development of the disease and its progression." (PMID 35877415, 2022). "In the present study we found that susceptibility to and the severity of endometriosis are associated with polymorphisms in the HLA-G, LILRB1 and LILRB2 genes." (PMID 29234882, 2018). "The putative role of HLA-G in the etiopathogenesis of endometriosis may be strengthened by our further observation that the disease is also associated with polymorphism in LILRB1 and LILRB2 genes coding for HLA-G receptors." (PMID 29234882, 2018). "Certain polymorphisms of HLA-G protected against endometriosis, and polymorphisms of LILRB1 and LILRB2 were associated with susceptibility to endometriosis and its progression." (PMID 35628346, 2022). "The AA genotypes of the rs41308748 polymorphism of the LILRB1 gene and AG rs383369 of the LILRB2 gene predisposed to endometriosis and its progression." (PMID 34638893, 2021). "The AA genotypes of rs41308748 polymorphism of the LILRB1 gene and the AG genotypes of rs383369 polymorphism of the LILRB2 gene predisposed to endometriosis and its progression." (PMID 33153202, 2020). "The analysis of the polymorphism of inhibitory LILRB1 and LILRB2 genes showed that endometriosis in the Polish population is associated with an increased frequency of 5651AA (5651G > A; rs41308748) genotype of LILRB1 gene." (PMID 31540116, 2019). "The study of Polish scientists analyzed whether polymorphisms of HLA-G, KIR2DL4, LILRB1 and LILRB2 genes may affect susceptibility to endometriosis and disease progression." (PMID 34638893, 2021). "Endometriosis is also associated with allelic variants of HLAG, thus suggesting that the LILRB1/HLA-G interaction may play a part in the inhibition of NK cell activity and the development of the disease." (PMID 31540116, 2019). "In this study we investigated whether HLA-G, KIR2DL4, LILRB1 and LILRB2 polymorphisms may influence susceptibility to endometriosis and disease progression." (PMID 29234882, 2018). "Therefore, the aim of this retrospective study was to evaluate the association of the SNPs in genes coding for KIR2DL4, LILRB1 and LILRB2 receptors and their ligand HLA-G with susceptibility to and severity of endometriosis as potential non-invasive markers for the diagnosis of this disease." (PMID 29234882, 2018). "Binding of human leukocyte antigen (HLA) G to its receptors LILRB1 and LILRB2 on NK cells is important in the pathogenesis of endometriosis." (PMID 35628346, 2022). "On the other hand, due to the upregulated expression of the inhibitory receptors observed in endometriosis, the inhibition of KIR2DL1, LILRB1/2, and NKG2A by monoclonal antibodies may have therapeutic effects on endometriosis." (PMID 36865552, 2023). "The most important conclusion was that HLA-G and the receptors LILRB1 and LILRB2 may play a crucial role in eliminating endometriotic cells and the development of endometriosis." (PMID 35628346, 2022).
multiple myeloma (7 papers, 2012 to 2025). "LILRB1 was identified in circulating CD56dim NK cells from patients with prostate cancer and multiple myeloma, and LILRB1 expression was upregulated compared to healthy donors." (PMID 40849493, 2025). "For example, leukocyte immunoglobulin-like receptor B1 (LILRB1) helps protect multiple myeloma cells from ferroptosis by maintaining cholesterol homeostasis." (PMID 41245411, 2025). "An anti-LILRB1 antibody enhanced NK cell killing against multiple myeloma and breast cancer cell lines in vitro." (PMID 40849493, 2025). "The authors identify the transmembrane receptor LILRB1 as a potential target as it protects myeloma cells from ferroptosis by facilitating cholesterol uptake and maintaining cholesterol homeostasis and squalene levels." (PMID 38982045, 2024). "The expression of LILRB1 demonstrated a heterogeneity across patient samples, with a common occurrence in primary patient myeloma cells." (PMID 38982045, 2024). "LILRB1 is expressed on a significantly larger proportion of NK-cells in patients with multiple myeloma and CLL than in healthy donors." (PMID 39696628, 2024). "In addition to these observational data, overexpression of LILRB1 in myeloma cell lines induced downregulation 13 out of 116 genes whose products are involved in the pathogenesis and progression of MM." (PMID 39696628, 2024). "Lentiviral transduction was employed to force LILRB1 expression in human myeloma cell lines." (PMID 35076022, 2022). "Moreover, peripheral NK cells from multiple myeloma (MM) and prostate cancer patients express markedly higher levels of LILRB1 when compared with those from healthy donors, which may hinder NK tumoricidal effects." (PMID 35076022, 2022). "Furthermore, in CD138 + plasma cells, a decrease in both mRNA and surface protein expression of LILRB1, LILRB2 and LILRB3 was decreased in myeloma vs MGUS." (PMID 39696628, 2024).
breast cancer (6 papers, 2020 to 2024). A primary or metastatic malignant neoplasm involving the breast. "Previous studies have found that LILRB1 promotes tumor development, such as lung cancer, breast cancer, and pancreatic cancer, which can significantly enhance the movement and migration ability of cancer cells and promote tumor metastasis." (PMID 34485116, 2021).
chronic lymphocytic leukemia (6 papers, 2018 to 2024). "For example, antibody masking of LILRB1 was demonstrated to promote the activation of NK cells from chronic lymphocytic leukemia (CLL) patients, to enhance NK cell proliferation when combined with the immunomodulatory drug lenalidomide and to promote lysis of CLL cells." (PMID 37781391, 2023). "Importantly, complementing rituximab and CD47-IgGσ, LILRB1-IgGσ increased ADCP of chronic lymphocytic leukemia (CLL) or lymphoma cells isolated from patients." (PMID 36389667, 2022). "The anti-LILRB1 antibody was found to significantly enhance ADCP when combined with CD20 and CD47 antibodies by analyzing different B-NHL cell lines and tumor cells from chronic lymphocytic leukemia (CLL) or mantle cell lymphoma (MCL) patients." (PMID 36389667, 2022).
COVID-19 (6 papers, 2021 to 2024). A disease caused by infection with severe acute respiratory syndrome coronavirus 2. "All three proteins enriched in lymphoid organs, i.e., STAB2, Leukocyte Immunoglobulin-Like Receptor B1 (LILRB1), and CR2, had decreased serum levels in COVID-19 patients." (PMID 37739942, 2023). "Hence, the lack of inhibition due to lower LILRB1 levels in patients with severe COVID-19 could contribute to hyperinflammation." (PMID 37739942, 2023).
HIV-1 infection (6 papers, 2008 to 2023). The type species of lentivirus and the etiologic agent of acquired immunodeficiency syndrome (AIDS). "LILRB1 has been found overexpressed on NK cells after HIV-1 infection and these LILRB1+ NK cells control virus replication in DCs." (PMID 38022598, 2023). "We used previously characterized HLA allotype-specific binding capacities of LILRB1 and LILRB2 as well as data from a large cohort of HIV-1-infected individuals (N = 5126) to test whether LILR-HLA class I interactions influence viral load in HIV-1 infection." (PMID 24603468, 2014).
acute myeloid leukemia (5 papers, 2020 to 2025). Acute myeloid leukemia (AML) is a group of neoplasms arising from precursor cells committed to the myeloid cell-line differentiation. "Additionally, we identified LILRB1 in monocytic acute myeloid leukemia (AML) and demonstrated LILRB1 CAR-T cell cytotoxicity against AML cell lines in vitro and in vivo." (PMID 40186066, 2025). "LILRB1 and LILRB4 expression, independently, are highly sensitive for monocytic differentiation in acute myeloid leukemia (M-AML)." (PMID 39696628, 2024).
autoimmune disease (5 papers, 2019 to 2025). A disorder resulting from loss of function or tissue destruction of an organ or multiple organs, arising from humoral or cellular immune responses of the individual to their own tissue constituents. "Thus, impaired LILRB1 function or expression has been implicated in the pathogenesis of several autoimmune diseases." (PMID 41562090, 2025). "Defects in LILRB1 function have been associated with several autoimmune diseases." (PMID 41188636, 2025). "This study demonstrates that a germline loss-of-function variant in LILRB1 could lead to autoimmune diseases." (PMID 36104364, 2022).